METTL25B (methyltransferase like 25B)
Synonyms: C1orf66; RRNAD1; CGI-41
Tractability: Antibody: UniProt predicts a signal peptide or a membrane-spanning region. PROTAC: ubiquitination databases record sites on it.
Gene: Protein-coding gene on chromosome 1 (156,728,442 to 156,736,960, forward strand). Ensembl gene ENSG00000143303.
Subcellular location: Membrane
Subcellular location (Human Protein Atlas): Nucleoli; Cytosol
Gene Ontology:
Molecular function: rRNA (adenine-N6,N6-)-dimethyltransferase activity
Biological process: rRNA modification
Cellular component: membrane
Genetic constraint (gnomAD): Loss-of-function variants: 33 observed, 43.94 expected, observed/expected ratio (o/e) 0.75, 90% interval 0.57 to 1. The upper end of that interval is the gene's LOEUF score, 1, which puts it in group 4 of 6, group 1 being the genes least tolerant of losing a copy. Missense variants: 500 observed, 575.23 expected, observed/expected ratio (o/e) 0.87, 90% interval 0.81 to 0.94. Synonymous variants: 206 observed, 241.58 expected, observed/expected ratio (o/e) 0.85, 90% interval 0.76 to 0.96.
Homologues: Orthologues: chimpanzee METTL25B (99% identical), macaque METTL25B (99% identical), pig METTL25B (93% identical), guinea pig METTL25B (91% identical), rabbit METTL25B (89% identical), rat Mettl25b (87% identical), mouse Mettl25b (87% identical), tropical clawed frog mettl25b (56% identical), zebrafish mettl25b (45% identical), Drosophila melanogaster CG2906 (31% identical), Caenorhabditis elegans F25H2.12 (28% identical). Paralogues in human: METTL25 (25% identical).
Diseases named in the same sentence as METTL25B in open-access papers:
METTL25B is named in the same sentence as 2 diseases in open-access papers, as found by Europe PMC text mining. Sharing a sentence is not in itself a finding about the gene and the disease. The quoted sentences say what the papers report.
cancer (1 paper, 2021). A tumor composed of atypical neoplastic, often pleomorphic cells that invade other tissues. "The TCGA Pan-Cancer cohort showed six genes [METTL1, METTL11B, EEF1AKNMT, METTL18, EEF1AKMT3 (METTL21B), RRNAD1 (METTL25B)] with high-level amplifications above 2%." (PMID 34285249, 2021).
METTL25B also shares sentences with these, for which no sentence is quoted: leukemia (1 paper).